IL22 (interleukin 22)
Diseases named in the same sentence as IL22 in open-access papers (continued):
Sharing a sentence is not in itself a finding about the gene and the disease.
tumor (continued). "IL-22-mediated anti-inflammatory effect might further impair the anti-tumor function of T-cell." (PMID 32649314, 2020). "In sharp contrast, ILC3-produced IL-17 and IL-22 may also promote tumor immunity in other settings." (PMID 28536374, 2016). "Furthermore, IL-22 was shown to reduce tumor growth in a breast cancer model." (PMID 28536374, 2016). "However, there is a theoretical hazard in FBXW12 antagonism, as unchecked cytoproliferation may drive neoplasia and some authors implicate IL-22 signaling in inflammatory disease." (PMID 26171402, 2015). "While in the short term IL-22-mediated survival and proliferation of epithelial cells may favor tissue healing and repair, prolonged IL-22 signaling, and sustained epithelial proliferation may drive tumor formation." (PMID 24982658, 2014). "Increased IL-22 and IL-22R expression could accelerate tumor growth in transplant patients." (PMID 23667456, 2013). "The aggressive nature of TSCC may result from at least two opposing forces: a) increased T regs and decreased CD8+ T cells, leading to decreased immune surveillance, and b) increased exposure to IL-22, which may provide a proliferative stimulus and accelerate tumor growth." (PMID 23667456, 2013). "Some studies support the notion that IL-22 may play different roles in different tumor cells." (PMID 21625390, 2011). "We next determined whether inhibition of tumor growth by IL-22 involves the induction of apoptosis." (PMID 21625390, 2011). "Serum IL-22 levels were measured by ELISA, and the density of CD163+ cells in the tumor tissue was analyzed immunohistochemically." (PMID 41752653, 2026). "IL-22 has been involved in mucosal defense, tissue repair, and wound healing, but also with CRC tumor progression through the activation of the STAT3 pathway, promoting cancer cell self-renewal and tumorigenesis." (PMID 41425582, 2025). "These cells are characterized by the production of IL-22 and also exhibit a dual role in CRC, acting in tissue repair in both early-stage disease and tumor progression as the inflammation becomes chronic." (PMID 41425582, 2025). "Once in close proximity to the tumor cells, these Tc17 cells engage in a reciprocal signaling cascade, secreting interleukins (IL-16, IL17, IL-22, and IL-26), thereby forming a vicious cycle that promotes the progression of tumor cells." (PMID 40452847, 2025). "On the other hand, in the HCC microenvironment, IL-22 is mainly secreted by CD4+ T cells and accelerates tumor progression by promoting angiogenesis and immune escape." (PMID 41562076, 2025). "In addition, IL-22 may also support tumor growth by promoting angiogenesis." (PMID 41019044, 2025). "Th22 cells, which secrete interleukin 22 (IL-22), have a variable role in regulating EMT depending on the tumor microenvironment." (PMID 40362280, 2025). "Previous studies have demonstrated that Th cell-derived IL-22 induces CD155 overexpression in lung tumor cells, impairing natural killer (NK) cell function via CD226 internalization and promoting tumor metastasis." (PMID 41562076, 2025). "NCR+ ILC3s tend to be anti-tumoral, producing IL-22 and TNF in contexts such as early-stage lung cancer and mucosal immunity, whereas NCR- ILC3s typically produce IL-17 and support tumor growth in CRC, liver, and pancreatic cancers." (PMID 40963622, 2025). "Cytokines produced by Th17 cells, including IL‐17 and IL‐22, are elevated in MPE and contribute to tumor microenvironment remodeling and interactions between tumor and immune cells." (PMID 40392144, 2025). "Gastric tumors exhibit increased infiltration of IL-22+ CD4+ T cells, with infiltration levels correlating with tumor stage and predicting poor prognosis." (PMID 40806452, 2025). "Furthermore, the presence of tumour cells and the associated inflammation may lead to atypical cytokine secretion patterns, which may explain the lack of correlation between IL-21 and IL-22 in this group, but further detailed studies are needed." (PMID 40729006, 2025).
tumor (continued). "At the same time, the decrease in MMP-2, MMP-9 SNAI1 and TWIST1 protein levels in IL-22 + LY294002 cells indicated that inhibition of the PI3K/AKT signaling pathway reduced MMP expression, attenuating tumor cell invasion and metastasis." (PMID 39073546, 2024). "Specifically, alterations in cytokines such as IL32, IL22, IL17F, IL17A, IL16, IL15, and HMGB1 can create an immunosuppressive tumor microenvironment in CTCLs to facilitate immune evasion and tumor progression." (PMID 39409988, 2024). "Consistently with in vitro results, KIR-ESS peptide reduced tumor growth in athymic nude mice bearing SCC xenografts, especially when xenografts were subjected to IL-22 administration." (PMID 38975347, 2024). "Our findings, in conjunction with previous studies, show that the signaling pathway involving IL22 and TGFB1 helps establish a microenvironment that promotes epithelial-mesenchymal transitions, malignancy progression, and tumor formation." (PMID 38456503, 2024). "Promote tumor progression through IL17, IL22 and IL26 signaling or Tc17 (IL-17CD8 T cells) differentiation into exhausted T cells." (PMID 39906741, 2024). "Th17 cells can suppress tumor growth and metastasis and promote cancer cell apoptosis by secreting TNF-α, the soluble dimer cytokine interferon (IFN)-γ, IL-17, IL-21, and IL-22." (PMID 39534095, 2024). "Dysbiosis in the breast microbiome can lead to inflammation in breast tissue, increasing M2-like macrophage infiltration, enhancing levels of interleukin (IL)-23, IL-22, CXCL-1, and CCL-2, and accelerating fibrosis within the tumor environment." (PMID 39717276, 2024). "SOCS1 and SOCS3 expression is reduced in tumor lesions of BCC and SCC, as compared to other skin inflammatory conditions such as psoriasis, despite the high number of IL-22-secreting tumor-infiltrating lymphocytes." (PMID 38975347, 2024). "It is also known that PI3K-AKT-mTOR signaling pathway activation via CAF-derived secretion, such as through CXCL12, VCAM1, IL-22, CXCL5, HGF, and SPARC, induces tumor proliferation, migration, and stemness." (PMID 37264057, 2023). "The recently study reported that IL-26 is involved in the production and promotion of MPE by enhancing CD4+IL-22+ T-cell differentiation and inhibiting CD8+ T-cell tumor-killing activity." (PMID 36776832, 2023). "In conclusion, whereas both ectopic T-BET and EOMES overexpression in ILC3s completely block IL-22 secretion, only T-BET overexpression increases IFN-γ secretion as well as cytotoxicity against tumor target cells." (PMID 36330517, 2022). "Using two different mouse models, we found that IL-22 promoted HCC development, while IL-22BP led to reduced tumor growth." (PMID 36551508, 2022). "After the NLRP3 inflammasome is activated, it causes an inflammatory cascade reaction, leading to the release of pro-inflammatory factors such as IL-1β, IL-18, IL-22, TNF-α, and the activation of inflammation-tumor signaling pathways such as NF-κB." (PMID 35292015, 2022). "Some proteins, such as IL22, CCL20, and MMP9, all shown to be involved in tumor progression were exclusively higher in serum from rats with MLL-tumors." (PMID 35551231, 2022). "T lymphocytes mediate tumor immunity by secreting various cytokines into the TME, such as IL-2, IL-4, IL-5, IL17, IL-21, IL-22, and IFN-γ." (PMID 35464411, 2022). "The cytokine TGF-β induces the production of IL-22 in IL-17-positive TH17 cells and, subsequently, tumor progression." (PMID 36611932, 2022). "After the treatment, positive correlations of mSWAT with the levels of IL22, IL33, and TNF-α in the tumor tissue were found." (PMID 35237320, 2022). "Beside interleukin-6 (IL-6), the high level of which is observed in patients with a high mortality rate, other cytokines IL-17A, IL-22, and transforming growth factor -β (TGF-β) are expressed at the tumor level." (PMID 36361758, 2022).
tumor (continued). "While tumor growth was similar with reduced Th22 in the 4T1-IL6-KO, the potential effects of Th22 and, by extension, IL-22 on metastatic burden warrant further study." (PMID 36142210, 2022). "IL-17, IL-21, IL-22, TNF-α and IL-6 are also produced in excess in individuals with CRC and synergistically promote tumor growth." (PMID 35739324, 2022). "The transdifferentiating cells lose the capability to produce IL-22, while gaining IFN-γ producing capacities and cytotoxicity against tumor cells." (PMID 36330517, 2022). "Hence, targeting Th22 cells and IL-22 may provide a new perspective for tumor therapy." (PMID 35669104, 2022). "Although the role of IL-22 in cancer has not been well-elucidated and it is controversial, it has been described that it has a positive prognosis in this type of cancer, relying on its capacity to induce a cross-talk between tumor cells and immune cells associated with a favorable clinical outcome." (PMID 36296703, 2022). "We have shown that deletion of IL-22 in a KM-LUAD mouse model suppressed tumorigenesis, altered the TME to an anti-tumor phenotype, and reduced stemness properties of tumor cells." (PMID 35406557, 2022). "In CRC, ILC3s produced IL-22 which activated STAT3 phosphorylation signaling to promote the development and invasion of tumor." (PMID 36246629, 2022). "We therefore assessed the production of several effector molecules important for T cell mediated tumor immunity (IFN-γ, GrB, IL-2, IL-17, IL-22, TNF) following polyclonal stimulation with PMA and Ionomycin." (PMID 33885944, 2021). "In contrast to these cytokines, IL-17-producing MAIT cells (median 0.1% in tumor-derived vs 0.4% in unaffected colon MAIT cells) and IL-22-producing MAIT cells (median 0.5% vs 0.6%) were scarce in both tissues." (PMID 33885944, 2021). "In NSCLC patients, IL-22 was greater in matched tumor tissue than MPE, and IL-22 expression in MPE promoted cancer cell migration, and protected cancer cells from apoptosis by chemotherapies." (PMID 33987104, 2021). "Another study found that IL-22 exposure increased the expression levels of phosphorylated-AKT, EGFR, and ERK in the tumor microenvironment after gefitinib treatment versus the control group." (PMID 33466795, 2021). "Th17-like Tregs that expressed IL-17, IL-22, IL-2, TNF and RORγt but in parallel maintained Foxp3 expression markedly enhanced anti-tumor immunity." (PMID 34539668, 2021). "While most studies suggest that diverse NKT cells inhibit anti-tumour immunity, iNKT cells contribute to natural tumour surveillance with immediate cytokine secretion (IFN-γ, TNF, IL-13, IL-17, IL-4, IL21, IL-22) and FasL/TRAIL pathways." (PMID 33499101, 2021). "IL-22 binds to the IL-10R2 and IL-22R1 receptor complexes, activating the transcription factor STAT3, thereby promoting tumor progression." (PMID 34300224, 2021). "attempted to introduce new therapies based on Th17 lymphocytes which produce IL-17A, IL-17F, IL-21, IL-22, IL-26, IL-6, TNF-α and suppress tumour progression through enhanced antitumor immunity in OC." (PMID 34621670, 2021). "The infiltration of cellular sources of IL-22 including Th22 and CD4+ T cells in the intratumoral tissue increases, corresponding to the stage of tumor." (PMID 33042126, 2020). "The lower tumor development in mice harboring TGF-β-DNR CD4+ T cells correlated with a reduced frequency of IL-17A+IL-22+ CD4+ T cells, whereas IL-17A-IL-22+ CD4+ T cells were unaffected." (PMID 32451418, 2020). "In 4T1 tumor tissue, ILC3 is a major cellular source of IL-22 which can be increased by giving IL-1β and IL-23." (PMID 32649314, 2020). "With the elevated IL-17 and IL-22 levels in STAT1−/− mice, the colonic epithelial cell proliferation increases while the tumor apoptosis rate decreases in the early stage of tumor formation." (PMID 32670290, 2020). "When looking into the soluble inhibitory receptor of IL-22, a decrease in the amount of IL-22BP producing CD4+ T cells in the tumor tissue was found." (PMID 32100077, 2020).
tumor (continued). "In another study using the CAC mouse model, depletion of innate lymphoid cells, IL-22, IL-17, or IFN-γ resulted in decreased tumour burden." (PMID 32635383, 2020). "IL-22 stimulates STAT3 activation in intestinal epithelial cells to promote cell proliferation, playing a predominant role in the maintenance of tumor development." (PMID 33193381, 2020). "Tumor cytokines’ dynamics indicate that as the tumor grows, HMGB1, IFN-γ and μ1 (IL-6, IL-17, IL-21, IL-22) increase in density, but TGF-β and μ2 (IL-10, CCL20) stay relatively constant." (PMID 33291412, 2020). "Specifically, TGF-β1 increases the population of IL-22-producing Th17 cells via activation of PI3K signalling and thereby promotes tumour growth, aggressiveness, and treatment resistance through the subsequent uncontrolled high levels of IL-22." (PMID 33114183, 2020). "One interesting approach can be the co-activation of macrophages (MΦs) (retinoic acid), NK cells (IL-15, IL-22, and IL-23), cytotoxic T cells (CTLs) (IL-2, TNF-α, IFN-γ), and the acquisition and presentation of tumor antigens by dendritic cells." (PMID 33276556, 2020). "Sustained IL-22 elevation and subsequent STAT3 activation were found with up-regulation of downstream genes in HCC mouse models, promoting tumor development and metastasis." (PMID 30824840, 2019). "NK cells exert its function on pathogens, tumor cells, stressed hepatocytes, and HSCs via the production of cytokines (IFN-γ, TNF-α, IL-10, IL-12, IL-22, etc.)and cytotoxic molecules (granzyme B, Perforin, etc.)both in direct or indirect fashion." (PMID 31500589, 2019). "We furthermore show that TYK2 is activated by an autocrine loop involving IL-10 and IL-22 and that STAT1 and STAT3 are essential mediators of aberrant tumor cell survival through activation of the pro-survival protein MCL1." (PMID 30131584, 2019). "However, IL-22 could be secreted not only by immune cells, but also by tumor cells." (PMID 30473538, 2018). "Also the role of Th17-type ILCs (ILC3) is ambiguous, since production of IL-17 and IL-22 favour tumour growth on one side, while, they may also interact with tumour cells via natural cytotoxic receptors or by forming tertiary lymphoid structure that results in cancer cell elimination." (PMID 29558948, 2018). "IL-22 promotes tumorigenic functions, by activating STAT3 phosphorylation and inducing mitogenic and other pro-tumor genes in several tumor lines, including BCC and SCC lines." (PMID 28445952, 2017). "As a member of the IL–10 cytokine family, IL-22 is a potent activator of STAT3, having an important role in tumorigenesis and tumor development." (PMID 28445985, 2017). "As a potent STAT3 activator, IL-22 is a member of the IL-10 cytokine family, principally produced by Th22 and Th17 subsets of CD4+ T cells which play important roles in tumor development." (PMID 28445985, 2017). "In particular, IL-22 promotes proliferation and migration of BCC and SCC cell lines, as well as tumor growth in an in vivo xenograft model." (PMID 28445952, 2017). "Aimed at rescuing SOCS3 activity in these tumor contexts, a SOCS3-derived peptide, named KIR-ESS, was synthesized, and its ability in suppressing IL-22-induced responses was evaluated in healthy and transformed keratinocytes." (PMID 28445952, 2017). "Our attempt to inhibit the IL-22 signaling by reinforcing the inhibitory SOCS3 action was supported by our observation that SOCS3 is poorly expressed in the BCC and SCC tumor lesions." (PMID 28445952, 2017). "We found that in vivo tumor growth was potently reduced by KIR-ESS administration, especially when xenografts were subjected to IL-22 treatment." (PMID 28445952, 2017). "IL-22-stimulated DLD-1 cells and paralleled cells were injected subcutaneously into these mice and the resulting tumor size and mass were measured." (PMID 28445985, 2017).
tumor (continued). "The breadth of responses includes anti-tumor effector (Granzyme B, IFN-γ, MIP-1α, TNF-α), stimulatory (GM-CSF, IL-2, IL-8), regulatory (IL-4, IL-13, IL-22), and inflammatory (IL-6, IL-17A) functions." (PMID 29157295, 2017). "At baseline, mRNA expression of IL-17, IL-23, IL-22 and IFN-γ was determined in 25 of 41 (60.9%) BCC tumor specimens and in all 8 control samples." (PMID 28829805, 2017). "IL-22 maintains the integrity of epithelial cells; TNF-α is a pro-inflammatory cytokine that exerts anti-tumor and anti-pathogen effects, and IL-8 and IL-2 enhance leukocyte recruitment and proliferation." (PMID 28271447, 2017). "IL-22 signaling directly activates STAT3 in epithelial cells and increases stemness and tumorigenic potential in tumor cells through the methyltransferase DOT1L." (PMID 27148488, 2016). "However, aberrant proliferation induced by IL-22 may promote tumor growth." (PMID 28536374, 2016). "To further assess the expression of IL-22 within the tissue, we performed reverse transcriptase-PCR (RT-PCR) on mRNA extracted from SCC, TSCC, their respective adjacent non-tumor bearing skin and normal skin from healthy volunteers." (PMID 23667456, 2013). "The presence of the Th17-related cytokine transcripts, IL-17A (IL-17), IL-21 and IL-22 mRNA, and of GFP was analyzed in extracts from the eyes 19 days after inoculation of tumor cells or injection of PBS." (PMID 21949734, 2011). "The analysis shows that the concentrations of IL-21 and IL-22 do not differ significantly depending on the malignancy grade of the tumour." (PMID 40729006, 2025). "Additionally, γδ T cells usually produce higher amounts of anti-tumor cytokines (such as TNF and IFN-γ) than pro-tumor cytokines (for instance: IL-4, IL-10, IL-17, IL-22, and IL-35) within the TME, reflecting their prognostic value in cancer patients." (PMID 40148988, 2025). "Of note, a most recent study proved that IL-22 could upregulated anti-apoptotic and metastatic genes in HCC cells by triggering PI3K/AKT activation, resultantly promoting tumor cell proliferation and invasion." (PMID 38596684, 2024). "In our HCC resection cohort, analysis of HCC tissue samples revealed a significantly higher expression of IL-22 in tumor tissues compared to adjacent non-tumor tissues." (PMID 38596684, 2024). "Indeed, IL-22, after binding IL-22R, leads to STAT3 pathway activation and is related to the progression of different neoplasms, including pancreatic, colon, breast, and lung cancers." (PMID 38607023, 2024). "Meanwhile, the increase in MMP-2 MMP-9, SNAI1 and TWIST1 protein levels in the IL-22 group suggests that IL-22 may regulate MMP expression by activating the PI3K/AKT signaling pathway, enhancing tumor cell invasion and metastasis." (PMID 39073546, 2024). "In gastric cancer, IL17 cells may promote tumor progression through IL17, IL22 and IL26 signaling or Tc17 (IL-17CD8 T cells) differentiation into exhausted T cells." (PMID 39906741, 2024). "To set the basis for a future therapy making the best use of IL-22 on liver regeneration without triggering tumor progression, we analyzed the gene expression changes in the remnant liver upon IL-22 neutralizing post-PVL." (PMID 38533053, 2024). "Despite the substantial roles of IL-17 and IL-22 in inducing angiogenesis, facilitating EMT, and expressing matrix metalloproteinases (MMPs) to promote tumor growth and tumor metastasis, there is currently a dearth of literature specifying the specific sources of these two cytokines." (PMID 38840908, 2024). "The JAK3-STAT3 pathway could act in concordance with IL-22 to enhance the expression of BTN2A1, which likely leads to increased tumor cell killing by Vγ9Vδ2 T cells for enhanced potential as immunotherapy against the cancer." (PMID 39769218, 2024). "Whether the use of P4 treatment of NPC cells can achieve physiological concentration of IL-22 for BTN2A1 induction remains to be investigated, as the amount produced is most likely less than tumor-resident lymphoid cells." (PMID 39769218, 2024).